GATA3 (GATA binding protein 3)
Diseases named in the same sentence as GATA3 in open-access papers (continued):
Sharing a sentence is not in itself a finding about the gene and the disease.
bronchiolitis (1 paper, 2021). Inflammation of the bronchioles characterized by swelling of the bronchioles and mucus accumulation. "Our study measured the levels of RORα and GATA-3 in the peripheral blood of patients with bronchiolitis." (PMID 33514798, 2021). "The results showed that the expression of transcription factors RORα and GATA-3 in the bronchiolitis group was higher than that in the normal control group (P < 0.05)." (PMID 33514798, 2021). "In summary, our study found that the specific transcription factors GATA-3, RORα and IL-17RB specifically expressed by the ILC2s in the bronchiolitis group had higher mRNA expression levels than the normal control group." (PMID 33514798, 2021). "Based on RORα and GATA-3 as the specific markers of ILC2, it is suggested that ILC2s increase and activate in the peripheral blood of patients with bronchiolitis." (PMID 33514798, 2021).
Candida infection (1 paper, 2024). "In this line, it has been demonstrated in murine studies that overexpression of Th2 transcription factor (GATA-3) enhances susceptibility to systemic Candida infection, possibly by reducing the production of IFN-γ." (PMID 39062060, 2024).
chlamydia (1 paper, 2020). "The increased expression of GATA-3 and IL-4 secretion of our study favors the dominance of Th2 cells, reflecting the switching of IFN-γ production by Th1 to IL-4 production by Th2 that probably subsequently result in the pathological development of chlamydia genital infection." (PMID 32413046, 2020).
choanal atresia (1 paper, 2021). Choanal atresia (CA) is a congenital anomaly of the posterior nasal airway characterized by the obstruction of one (unilateral) or both (bilateral) choanal aperture(s), with clinical manifestations ranging from acute respiratory distress to chronic nasal obstruction. "In humans, GATA3 associates with highly variable defects, such as HDR syndrome, microsomia and choanal atresia." (PMID 34033651, 2021).
chronic kidney disease (1 paper, 2025). Impairment of the renal function secondary to chronic kidney damage persisting for three or more months. "This case presents a 38-year-old female patient with recurrent urinary infections, hearing loss, and chronic kidney disease who underwent extensive laboratory, radiological, and genetic analysis which demonstrated a GATA3 mutation in the 10p15 location." (PMID 41019281, 2025).
chronic myelomonocytic leukemia (1 paper, 2016). A myelodysplastic/myeloproliferative neoplasm which is characterized by persistent monocytosis, absence of a Philadelphia chromosome and BCR/ABL fusion gene, fewer than 20 percent blasts in the bone marrow and blood, myelodysplasia, and absence of PDGFRA or PDGFRB rearrangement. "Importantly, GATA3 DNA hypermethylation implicates epigenetic therapies in GATA3low ETP-ALL, such as decitabine, a hypomethylating agent approved for the treatment of myelodysplastic syndrome, chronic myelomonocytic leukemia, and AML." (PMID 27658391, 2016).
chronic pyelonephritis (1 paper, 2023). "The light microscopic evaluation showed transitional metaplasia in the background of chronic pyelonephritis, confirmed by GATA3 nuclear immunohistochemical stain." (PMID 38024545, 2023).
coronary artery disease (1 paper, 2024). "Polymorphisms in genes associated with the regulation of calcium levels (CASR, CYP24A1, CARS, DGKD, DGKH/KIAA0564 and GATA3) and metalloproteinases (MMP-3 and MMP-9) were also associated with an increased risk of coronary artery disease and AMI." (PMID 38478535, 2024).
craniofacial microsomia (1 paper, 2021). "Furthermore, GATA3 associates with craniofacial microsomia, another highly variable disease." (PMID 34033651, 2021). "Our results provide strong evidence that GATA3 is responsible for craniofacial microsomia and likewise implicate Bmp pathway members in the etiology of microsomia." (PMID 34033651, 2021).
craniosynostosis (1 paper, 2023). Craniosynostosis is defined as the premature fusion of one or more cranial sutures leading to secondary distortion of skull shape resulting in skull deformities with a variable presentation. "GATA3 was among the most increased DEGs associated with coronal craniosynostosis, compared to controls, and has previously been shown to have roles in osteoblast survival and the healing of bone fractures, which could explain its increased expression seen in the coronal craniosynostosis phenotype." (PMID 36982425, 2023).
cutaneous melanoma (1 paper, 2022). A primary melanoma arising from atypical melanocytes in the skin. "We next examined whether GATA3+ Tregs accumulated at cutaneous melanoma sites in Braf/Pten mice and whether this was dependent on TSLP." (PMID 36107619, 2022).
dengue (1 paper, 2022). "In this work, we found that patients with dengue did not significantly express T-bet and ROR-γ, but they showed higher expression of GATA-3 and FOXP-3, particularly in patients that worsen to DHF." (PMID 35372587, 2022).
diabetic foot ulcer (1 paper, 2025). "They unveiled the potential association between important ceRNAs (JUNB, GATA3, hsa_circ_0049271, and hsa_circ_0074559) and infiltrating immune cells (CD8 + T cells and monocytes) with a diabetic foot ulcer." (PMID 40419622, 2025).
Duchenne muscular dystrophy (1 paper, 2024). Duchenne muscular dystrophy (DMD) is a neuromuscular disease characterized by rapidly progressive muscle weakness and wasting due to degeneration of skeletal, smooth and cardiac muscle.
eccrine carcinoma (1 paper, 2017). An adenocarcinoma with eccrine differentiation arising from the sweat glands. "Cutaneous eccrine carcinomas were positive for GATA3 in 36% to 68% cases." (PMID 28693610, 2017). "The only eccrine carcinoma in our study showed 4+ GATA3 staining (>75% cells)." (PMID 28693610, 2017).
edema (1 paper, 2024). An abnormal accumulation of fluid beneath the skin, or in one or more cavities of the body. "Methotrexate administration resulted in increased levels of TNF-α, MPO, GATA3, caspase-3, and pulmonary edema indices, while reducing the levels of TAC, SOD, Gpx, IL-10, T-bet, and FOXP3." (PMID 38245672, 2024).
encephalomyelitis (1 paper, 2023). Inflammation of the brain and the spinal cord. "Nevertheless, GATA3 is still critically required for encephalomyelitis, which is associated with a reduction in the expression of GM-CSF and its regulators." (PMID 37449212, 2023). "Altogether, our data demonstrate that dynamic GATA3 expression during Th17 cell differentiation is required for Th17-mediated encephalomyelitis in EAE." (PMID 37449212, 2023). "Interestingly, Tamoxifen-treated Cre-ERT2-Gata3fl/fl CD4 effector cells Tcra-/- recipients were resistant to transfer EAE in comparison to vehicle treated controls, indicating that late maintenance levels of GATA3 are also required for Th17-mediated encephalomyelitis." (PMID 37449212, 2023).
epithelioid mesotheliomas (1 paper, 2023). "It should be noted that most epithelioid mesotheliomas express GATA3, and some may also be positive for PAX8." (PMID 37461124, 2023).
fasciolosis (1 paper, 2026). "T‐bet (T‐box expressed in T cells protein) remained at the basal level, whereas expression of GATA‐3 (GATA‐binding protein 3) was dramatically increased in severe fasciolosis." (PMID 41503693, 2026). "The present study revealed that the expression of T‐bet was reduced, whereas the expression of GATA‐3 was increased and that GATA‐3 was predominantly expressed in fasciolosis, displaying a Th2 drift at the transcriptional level." (PMID 41503693, 2026).
gastric disease (1 paper, 2017). "Though not validated in the present study, it is logical to hypothesize that overexpression of GATA-3 in lymphocytes is a critical molecular mechanism for increased ILC2s and Th2 cells in H. pylori infection-associated gastric disease." (PMID 29138530, 2017).
glomerulonephritis (1 paper, 2022). A renal disorder characterized by damage in the glomeruli. "In particular, GATA3-expressing Treg cells represented the majority of Treg cells found in the kidney post induction of glomerulonephritis and expressed higher amounts of Treg cell effector molecules compared to GATA3-negative Treg cells." (PMID 35936011, 2022).
glomus tumor (1 paper, 2025). A rare benign or malignant mesenchymal neoplasm arising from cells that resemble the modified smooth muscle cells of the glomus body. "However, glomus tumors are negative for CD34, GATA3, and CD117." (PMID 39568313, 2025).
hearing disorder (1 paper, 2023). A disorder characterized by the partial or complete loss of the ability to detect sounds due to damage to the ear structures or inability of the brain to properly interpret or process the auditory signals it receives from the anatomic structures of the ear. "As commented in Results, 3 of these genes (Gata3, Kcnq4 and Kit) are associated to hearing disorders in both mouse and human." (PMID 36999169, 2023).
hemophagocytic syndrome (1 paper, 2016). "We also compared the rates of hemophagocytic syndrome between the 2 groups and found a higher incidence for the GATA3+ group (Fisher, p < 0.05)." (PMID 27589565, 2016). "In addition, GATA3 expression was correlated with two clinical parameters, B symptom presentation (Pearson, p = 0.000) and hemophagocytic syndrome incidence (Fisher, p = 0.041)." (PMID 27589565, 2016).
hookworm infection (1 paper, 2012). "Levels of mRNA encoded by the Th2/Th9 genes IL-4, IL-5, IL-13, IL-9 and GATA-3 appeared unaffected by hookworm infection using this technique." (PMID 22346753, 2012).
hydronephrosis (1 paper, 2025). Collection of urine in the renal pelvis that results in dilatation of the renal pelvis and calyces. "Mutation of Gata3 in mouse embryos cause hydronephrosis at birth, suggesting Gata3 factor is required for urinary tract mutation." (PMID 40034749, 2025).
Hydroureter (1 paper, 2008). The distention of the ureter with urine. "Hence the conditional inactivation of Gata3 leads to a broad spectrum of urogenital defects, including a high incidence of hydronephrotic kidneys and hydroureters." (PMID 19112489, 2008).
Hyperkeratosis (1 paper, 2017). Hyperkeratosis is a histopathological term defining a thickened stratum corneum and may be present in many different skin conditions, with many possible overlaps. "TSLP was detected in/around the epithelium of patients with OLP and hyperkeratosis, whereas TSLPR, CD11c (mDC), and GATA3 (Th2) were strongly expressed in the subepithelial layer only in OLP patients." (PMID 28278185, 2017).
idiopathic pulmonary fibrosis (1 paper, 2025). Idiopathic pulmonary fibrosis (IPF) is a nonneoplastic pulmonary disease that is characterized by the formation of scar tissue within the lungs in the absence of any known cause. "By degrading the mRNA of transcription factors Gata3 and Egr1, it indirectly suppresses the production of pro-fibrotic cytokines such as IL-5 and IL-13, thereby limiting the progression of idiopathic pulmonary fibrosis (IPF)." (PMID 41154702, 2025).
IgA nephropathy (1 paper, 2023). "Heterozygous GATA3 knockout mice showed reduced proliferation rates of mesangial cells possibly leading to defective repair processes and GATA3 was shown to be increased in rodent models of mesangioproliferative glomerulonephritis and in patients with IgA nephropathy." (PMID 38116790, 2023).
intervertebral disc degeneration (1 paper, 2018). "In a previous study, we demonstrated that PF could modulate Th1/Th2 cell imbalances by regulating the expression of the transcription factors T-bet and Gata-3 in intervertebral disc degeneration rats." (PMID 30627586, 2018).
intestinal polyposis (1 paper, 2015). "In addition, it has been shown that Gata-3 is required for IL-10 expression and IL-10 is critical for inhibiting intestinal polyposis." (PMID 26146642, 2015).
intestinal tumor (1 paper, 2015). "Taken together, our results show that Apc/Min+ Foxp3+ Tregs undergo robust expansion in the intestinal tumor microenvironment and these Treg have altered Gata-3 expression that is important for Treg function in vivo." (PMID 26146642, 2015).
ischemia (1 paper, 2025). A hypoperfusion of the BLOOD through an organ or tissue caused by a PATHOLOGIC CONSTRICTION or obstruction of its BLOOD VESSELS, or an absence of BLOOD CIRCULATION. "Furthermore, the existence of GATA3-positive macrophages adversely influences myocardial remodeling during ischemia or pressure overload, while the absence of these macrophages considerably improves cardiac function." (PMID 40271123, 2025).
latent infection (1 paper, 2021). "Another possible cause for the decrease in IFNγ production could be the production of the Tbet+GATA3+ double positive TH1 cells we observed during the latent infection." (PMID 35186781, 2021).
lentivirus infection (1 paper, 2018). Virus diseases caused by the Lentivirus genus. "Confocal fluorescence microscopy confirmed successful construction of MDA-MB-231 cells stably overexpressing N3ICD, with or without GATA-3 knockdown by lentivirus infection." (PMID 30100605, 2018).
lepromatous leprosy (1 paper, 2014). A chronic communicable infection which is a principal or polar form of leprosy. "In our study, GATA3 showed decrease in the dermal lesions of lepromatous leprosy as compared to normal skin." (PMID 24454972, 2014).
lupus nephritis (1 paper, 2025). Glomerulonephritis in the context of systemic lupus erythematosus. "However, the slight increase in GATA3 and IL‐4 in probiotic‐treated groups suggests potential subtle effects on Th2 pathways, which warrant further investigation, particularly in contexts where Th2 responses may play a secondary role, such as in lupus nephritis." (PMID 41334229, 2025).
lymph node disease (1 paper, 2021). "Significantly higher GATA3 expression levels were assessed in IC within CIS for lymph node disease (5.3 ± 1.1 vs. 3.3 ± 1.9; p = 0.044)." (PMID 33672843, 2021).
lymphoproliferative disorders (1 paper, 2023). "GATA-3 is a transcription factor which influences the development and differentiation of peripheral T cells, is specifically involved in the activation of the Th2 cytokine genes expression, and has been associated with allergic and lymphoproliferative disorders." (PMID 36835433, 2023).
male breast carcinoma (1 paper, 2018). A malignant neoplasm involving the male breast. "In our study we could show that NY-BR-1 and GATA-3 are highly sensitive breast markers in primary and metastatic male breast cancer." (PMID 29116378, 2018).
metaplastic breast carcinoma (1 paper, 2025). A group of invasive breast carcinomas characterized by the presence of an adenocarcinomatous component which is admixed with a dominant component that is composed of squamous cells, spindle cells, or mesenchymal cells. "Concordant with these findings, we noted a considerably higher positivity for TRPS1 in metaplastic breast carcinoma (100%) compared with GATA3 (42.9%) and SOX10 (66.7%)." (PMID 40025593, 2025). "TNBCs and metaplastic breast carcinoma, showed higher positivity of TRPS1, compared with GATA3 and SOX10." (PMID 40025593, 2025).
Mikulicz's disease (1 paper, 2022). "On comparing Mikulicz's disease patients with healthy individuals, CD4+GATA3+ Th2 cells are predominant and significantly increased in the affected salivary glands of Mikulicz's disease patients." (PMID 35769404, 2022).
minimal change nephrotic syndrome (1 paper, 2012). "Elevated GATA-3 mRNA levels in circulating mononuclear cells have been reported in patients with minimal change nephrotic syndrome." (PMID 22523590, 2012).
mole (1 paper, 2023). "The expressions of maternally imprinted genes were seen in all cases, except for one case of complete mole where GATA3 was negative." (PMID 37298606, 2023).
nephropathia epidemica (1 paper, 2012). "In a multivariate logistic regression model, maximum urinary cell GATA-3 mRNA levels were an independent risk factor for severe AKI in PUUV nephropathia epidemica." (PMID 22523590, 2012).
neuritis (1 paper, 2022). A neuropathy arising from inflammation of one or more nerves. "In contrast, AAV-Re-Gata3-GFP infection induces weak Map2 expression and limited neurite growth in GFP-positive neurocytes, while the GFP-negative neurons show strong Map2 staining and distinct neuritis (White arrow)." (PMID 36430332, 2022).
non-small cell lung carcinoma (1 paper, 2025). A group of at least three distinct histological types of lung cancer, including non-small cell squamous cell carcinoma, adenocarcinoma, and large cell carcinoma. "A prospective study involving 89 early-stage non-small cell lung cancer patients demonstrated that SBRT increased CD4+ and CD8+ T-cell levels and significantly changed transcription factors such as TBX21, GATA-3, and FOXP3." (PMID 40283008, 2025).
oncocytomas (1 paper, 2023). "Studies have found that GATA3 is expressed in distal nephrons, 51% of ChRCCs and 17% of oncocytomas." (PMID 36816543, 2023).
osteoporosis (1 paper, 2015). A condition of reduced bone mass, with decreased cortical thickness and a decrease in the number and size of the trabeculae of cancellous bone (but normal chemical composition), resulting in increased fracture incidence. "This knowledge motivates future studies to determine whether exogenous OPG can partially rescue diseases due to GATA3 deficiency such as HDR syndrome, and whether the increase of OPG expression by manipulation of GATA3 can prevent diseases such as osteoporosis." (PMID 26216189, 2015).
ovarian teratoma (1 paper, 2025). A non-seminomatous germ cell tumor arising from the ovary. "With regard to any potential association between HDR syndrome and ovarian teratomas, GATA3 protein is also considered a valuable marker for certain types of urinary bladder and urethral cancers, as well as for parathyroid gland tumours." (PMID 40932684, 2025). "We acknowledge that there is no certainty that the ovarian teratomas in this patient are related to the GATA3 variant or HDR syndrome, as this is a single case." (PMID 40932684, 2025).
Paget disease (1 paper, 2019). A malignant neoplasm composed of large cells with large nuclei, prominent nucleoli, and abundant pale cytoplasm (Paget cells). "However, GATA3 is helpful to exclude either secondary Paget disease of colorectal origin or high-risk HPV-associated neoplasm." (PMID 30711015, 2019).
pancreatic NEN (1 paper, 2025). "Detailed characterization of pulmonary NEC, pulmonary carcinoid, pancreatic NEN, ileal NEN, and MiNEN was performed using immunohistochemical staining to detect pan-cytokeratin (panCK), Thyreoglobulin (TG), Calcitonin (CT) and the transcription factors CDX2, SATB2, TTF1, GATA3, ARX and PDX1." (PMID 41145514, 2025).
papillary urothelial neoplasm (1 paper, 2023). "However, low-grade UC and papillary urothelial neoplasm of low malignant potential exhibited moderate GATA3 expression." (PMID 38161907, 2023). "In patients with papillary urothelial neoplasm of low malignant potential (PUNLMP), all the patients (n=3) showed a moderate positive expression of GATA3." (PMID 38161907, 2023).
pituitary carcinomas (1 paper, 2020). A primary or metastatic malignant neoplasm affecting the pituitary gland. "Pit-1 will be immunoreactive in pituitary carcinomas of the somatotroph, lactotroph, and thyrotroph lineages while SF1 and GATA3 will be immunoreactive in the carcinomas of the gonadotroph lineage." (PMID 32622369, 2020).
placental tumor (1 paper, 2024). "For example, GATA3 and AP2 gamma (TFAP2C), two TFs that were recently reported to cooperate with TEAD4 and VGLL1 to differentiate pluripotent stem cells into trophoblast stem cells, were also identified from our ChIP-seq analysis of breast and placental tumor cells." (PMID 38912065, 2024).